MYT1L (myelin transcription factor 1 like)
Diseases named in the same sentence as MYT1L in open-access papers (continued):
Sharing a sentence is not in itself a finding about the gene and the disease.
tumor (9 papers, 2013 to 2025). "Reduced expression of two genes, PTEN (a tumour suppressorpreviously implicated in MB) and MYT1L, was associated with pooroutcome." (PMID 24252690, 2013). "However, in DNA-PK-deficient cells, MYT1L functioned as a tumor suppressor by inhibiting cell proliferation and inducing a G1 arrest." (PMID 40362634, 2025). "It is also interesting to look at the effect of MYT1L on tumor growth in an in vivo tumor xenograft animal model using GFP-/MYT1L-M059J and GFP-/MYT1L M059K cells, further confirming our in vitro findings." (PMID 40362634, 2025). "Based on these evidences, we hypothesized that genetic variation in MYT1L gene might affects its function to regulate expression levels of sets of tumor-related genes, and consequently involves in carcinogenesis." (PMID 24015200, 2013). "The progression-free analysis found that FAM90A1, ETS2, STAT6, MYT1L, ING2 and KCNK1 are related to tumour regrowth." (PMID 32015217, 2020). "Some show marked differential expression in a single non-SHH subgroup,such as NFIA (Group 3 tumours) and FGF13 (Group 4 tumours), orin more than one subgroup (e.g. TGIF2 and MYT1L), suggestingthat these genes may be relevant to MB in general." (PMID 24252690, 2013).
cancer (6 papers, 2010 to 2025). A tumor composed of atypical neoplastic, often pleomorphic cells that invade other tissues. "Although MYT1L itself has not previously been reported to associated with carcinoma, it is highly homologous to MYT1 and the loss of MYT1 function may be compensated by MYT1L activity." (PMID 24015200, 2013). "Moreover, p21 has been shown to promote cell death in cancer cells via the activation of autophagy; the down-regulated p21 may be a causal player in attenuating apoptosis in HEK293 cells that express MYT1L." (PMID 40362634, 2025).
psychiatric disorder (3 papers, 2010 to 2020). A disorder characterized by behavioral and/or psychological abnormalities, often accompanied by physical symptoms. "The expression of the protein MYT1L, which is abundant in the brain, has never been studied for allelic association in any psychiatric disorder." (PMID 21048971, 2010). "The MYT1L protein plays a crucial role in CNS development, so it is rational to presume that changes in its expression level or function resulted from genetic variations could lead to psychiatric disorders." (PMID 24015200, 2013).
neurodegenerative disease (2 papers, 2010 to 2022). A disorder of the central nervous system characterized by gradual and progressive loss of neural tissue and neurologic function. "Each region also included key genes associated with addiction (Maoa, Ptprd, and Slit3), psychiatric illnesses (Maoa, Myt1l, Slc12a6, and Slit3), and neurodegenerative diseases (Apba1 and Slc12a6)." (PMID 20808911, 2010).
MYT1L also shares sentences with these, for which no sentence is quoted: developmental delay (5 papers); attention deficit-hyperactivity disorder (3); depression (2); Duchenne muscular dystrophy (2); type 2 diabetes (2); adenocarcinoma (1); adenoma (1); astrocytoma (1); B-Cell CLL (1); benign neoplasm (1); brain tumor (1); Childhood onset (1); childhood onset schizophrenia (1); congenital heart disease (1); diabetes (1); Down syndrome (1); Jacobsen syndrome (1); lymph node metastasis (1); lymphoma (1); Macrocephaly (1); medulloblastoma (1); neurological diseases (1); obesity syndrome (1); oligodendroglioma (1); panic disorder (1); parathyroid disease (1); Smith-Magenis syndrome (1); squamous cell carcinoma (1); Type-1 diabetes (1); ZIKV infection (1).